TLR2 (toll like receptor 2)
Diseases named in the same sentence as TLR2 in open-access papers (continued):
Sharing a sentence is not in itself a finding about the gene and the disease.
pneumonia (continued). "In this study, the risk of pneumonia and in particular of pulmonary IFD was significantly increased in patients with a TLR2 R753Q polymorphism although we are aware that these results are based on a rather low number of patients heterozygous for that SNP." (PMID 26963509, 2016). "TLR2−/− mice presented with more severe pneumonia having both organizing and necrotizing features involving multiple lobes of the lung and moderate to severe peribronchiolar inflammation." (PMID 23554897, 2013). "Already before surgery, the baseline of TLR2 expression on AM was significantly lower (27.7%) in patients who developed postoperative pneumonia." (PMID 24321282, 2013). "The three patients with postoperative pneumonia (9%) were characterized preoperatively by a lower baseline HLA-DR (−35.4%) and TLR2 expression (−27.7%)." (PMID 24321282, 2013). "The results presented here strongly argue against a significant role of TLR2 in host defense during S. pneumoniae pneumonia in the asplenic state." (PMID 22721450, 2012). "Using TLR2/4 double-deficient mice we show that TLR2 and TLR4 regulate IFNγ-secretion in vivo during pneumonia caused by C. pneumoniae." (PMID 22096480, 2011). "In mice pneumonia studies, TLR2, TLR5 and TLR9 were required for effective innate immune responses against L. pneumophila." (PMID 20615218, 2010). "To further confirm if S. pneumoniae also induces TLR2 expression in vivo, we examined S. pneumoniae- and PLY-induced TLR2 expression in vivo using S. pneumoniae-induced pneumonia and OM model in mice." (PMID 18664270, 2008). "An earlier study performed at our laboratory has shown an important role for TLR2 in the early host defence against S. pneumoniae pneumonia using serotype 3." (PMID 17711480, 2008). "We found that wt mice with untreated S. pneumoniae meningitis lived longer than infected mice with a genetic deletion of TLR2 or CD14 or both TLR2 and CD14." (PMID 17428319, 2007). "Using PCR-DNA sequence verdicts, the TLR2 (354 bp), CLEC4E (443 bp), PTX3 (363 bp), CXCL8 (300 bp), SOCS3 (480 bp) and IL15RA (378 bp) genes were found to have different SNPs in the amplified DNA bases linked to pneumonia." (PMID 40559821, 2025). "Also, Mycoplasma bovis is commonly found in calves with pneumonia, and in vitro studies have shown lipids derived from this bacteria activate the pro-inflammatory response in embryonic bovine lung cells in a TLR2 activation dependent manner." (PMID 39541407, 2024). "Researchers have shown TLR2 recognizes the lipopolysaccharides of Legionella pneumophila and induces chemokine-dependent cellular migration that is crucial for the host innate response in L. pneumophila-induced pneumonia." (PMID 37662905, 2023). "Moreover, individuals carrying either the TLR2-rs5743708 or the TLR4-rs4986791 polymorphisms exhibited a 3.6- and 2.5-fold increased probability for developing pneumonia and a more severe disease, respectively." (PMID 37766191, 2023). "Additionally, we clearly demonstrated that carriers of either TLR2-rs5743708 or TLR4-rs4986791 polymorphisms, as a whole group, displayed a significant risk for pneumonia development and more severe disease." (PMID 37766191, 2023). "•Ambient ASD (IT: 50 or 200 μg × 4 at weekly or 2 weekly intervals) exacerbates KP-induced pneumonia whilst accompanying in vitro studies suggest this is mediated by enhanced production of pro-inflammatory mediators via activation of TLR2 and NALP3 inflammasome pathways in alveolar macrophages." (PMID 34333291, 2021). "The aim of the study was to determine the molecular genetic prognostic criteria for the severity of pneumonia based on the analysis of the association of genetic polymorphisms of toll-like receptors (rs5743551 (TLR1), rs5743708 (TLR2), and rs4986790 (TLR4) loci) with the severity of NETosis." (PMID 34603755, 2021).
pneumonia (continued). "Pam3CSK4, a TLR2 agonist, equally stimulated anti-dsDNA IgA production in C4KO mice, suggesting complement C4 plays a role in subduing autoantibody production stimulated by cross-reactive antigens and TLR2 agonists associated with S. pneumonia." (PMID 34335607, 2021). "Additionally, in patients who developed postoperative pneumonia, we found significantly lower TLR2 levels on AMs even before surgery." (PMID 24321282, 2013). "We also explored the role of TLR2 upregulation in post-influenza pneumonia." (PMID 23369570, 2013). "We here investigated the impact of TLR2 on the outcome of pneumonia in splenectomized mice." (PMID 22721450, 2012). "Lipoteichonic acid (LTA) from S. pneumonia is able to activate TLR2 and CD14." (PMID 19371402, 2009). "pneumoniae strain, showing that TLR2 does not contribute to a protective immune response during pneumonia caused by a serotype 2 pneumococcus." (PMID 17711480, 2008). "In addition, we observed that carriers of TLR2-rs5743708 and TLR4-rs4986791 SNPs displayed a 3.7- and 2.2-fold increased risk for developing pneumonia, respectively, also affecting the risk for a more severe disease; however, the statistical differences were not marginally significant." (PMID 37766191, 2023). "However, TLR2-induced MyD88 activation is known to trigger an important inflammatory immune response and it is very critical for the clearance of P. aeruginosa-induced pneumonia." (PMID 34737734, 2021). "The TLR2 SNP rs5743708 is not linked with the other functional TLR2 SNP rs5743704 hence the amino-acid change 753Arg > Gln (rs5743708) may solely contribute to the revealed association of the TLR2 gene with pneumonia." (PMID 27725770, 2016). "However, our laboratory recently demonstrated that TLR2 does not play a key role in host resistance to pneumonia caused by a serotype 3 strain of S. pneumoniae." (PMID 17711480, 2008). "However, the link between TLR2 up-regulation and mixed infection in otitis media and pneumonia still remains unknown." (PMID 18664270, 2008). "Hence, these data show that TLR2 serves to limit the growth of S. pneumoniae PLN during pneumonia." (PMID 17711480, 2008). "In contrast, our group could not demonstrate a protective role for TLR2 in pneumonia caused by S. pneumoniae, showing similar bacterial multiplication and lethality after intranasal infection of TLR2 KO and WT mice." (PMID 17711480, 2008). "The genes TLR2, CLEC4E, PTX3, CXCL8, and IL15RA exhibited significantly higher expression levels in pneumonia-affected ewes compared to healthy controls." (PMID 40559821, 2025). "This study used a PCR-DNA sequencing technique to characterize the immunological (TLR2, CLEC4E, PTX3, CXCL8, SOCS3 and IL15RA) genes in ewes with pneumonia and healthy ewes." (PMID 40559821, 2025). "In a M. pneumoniae pneumonia mouse model, TFCO significantly reduced the lung damage, suppressed IL-1β, IL-6, and TNF-α production, and curbed TLR2 activation triggered by M. pneumoniae." (PMID 37894556, 2023). "During pneumonia, AECs recognize various pathogens due to the expression of different PRRs, including TLRs [TLR1, TLR2, TLR4, TLR5, TLR6 (Extracellular TLRs), and TLR3, TLR7, TLR8, and TLR9 (Intracellular TLRs)] and NLRs comprising inflammasome." (PMID 32849610, 2020). "Recently, we could demonstrate that functionally relevant TLR2 (Arg753Gln—rs5743708) and TLR4 (Asp299Gly—rs4986790, Thr399Ile—rs4986791) polymorphisms significantly contribute to infectious complications like sepsis and pneumonia in AML patients undergoing induction chemotherapy." (PMID 26963509, 2016). "Furthermore, TLR2 did not contribute to an effective antibacterial defense during post-influenza pneumococcal pneumonia, which normally is associated with a much stronger inflammatory response in the lungs than primary pneumonia." (PMID 22721450, 2012).
pneumonia (continued). "Here, we report that synthetic ligands for TLR2/6 and TLR9 induce robust protection against lethal influenza pneumonia, including from swine-origin H1N1 influenza." (PMID 22299046, 2012). "However, TLR2/6 and TLR9 have been shown to work synergistically to protect mice during lethal IAV-induced pneumonia." (PMID 37662905, 2023). "First, while endotoxin is a powerful stimulator of TLR2- and TLR4-mediated immune responses which play key roles in bacterial pneumonia-induced ALI, it does not fully recapitulate pneumonia caused by an infectious and proliferating pathogen." (PMID 36555499, 2022). "The TLR2-induced MyD88 activation is not required for the S. aureus clearance during pneumonia and only exerts the potent inflammatory immune response, but it plays a crucial role in P. aeruginosa clearance." (PMID 32849610, 2020). "Similar observation has been done in Acinetobacter baumannii-triggered pneumonia, suggesting that the dampening function of TLR2 during pneumonia is not bacterial species-specific." (PMID 30452654, 2019). "Human lung epithelial cells contribute to the clearance of attenuated K. pneumoniae by producing beta-defensins in a TLR2- and NOD1-dependent manner, which highlights the importance of NOD1 in respiratory pathogen elimination and in pathogen-evasion mechanisms in human pneumonia." (PMID 25253572, 2014). "For example, it has been reported that TLR2 does not play a major role in Streptococcus pneumoniae killing and disease after either systemic disease or pneumonia." (PMID 23724118, 2013). "We here focused on the role of TLR2 in defense during S. pneumoniae pneumonia in the asplenic host, considering that this TLR does not play a significant part in limiting bacterial growth in animals with an intact spleen." (PMID 22721450, 2012). "We demonstrate that even in absence of the spleen, TLR2 does not contribute to host defense during pneumonia with serotype 2 or 3 S." (PMID 22721450, 2012). "Also, TLR2-induced MyD88 activation was not required for the clearance of S. aureus during pneumonia." (PMID 34737734, 2021). "The TLR2, TLR4, and MyD88 deficiency did not alter the host response during lethal pneumonia." (PMID 32849610, 2020). "Thus, TLR2 activation does not have a significant role in the pathogen clearance and survival of the mice but is only required for the inflammatory immune response during Gram-positive bacterial (S. pneumoniae) pneumonia." (PMID 32849610, 2020). "However, since TLR2 may not contribute to host responses during post-influenza pneumonia, it was previously not clear whether increasing TLR2 expression would prevent or ameliorate this condition." (PMID 23369570, 2013). "Although the upregulation of TLR2 may be helpful against bacterial infection, it has been suggested that TLR2 does not contribute to host responses during post-influenza pneumonia, Therefore, it is not yet clear whether upregulation of TLR2 would be beneficial in such a scenario." (PMID 23369570, 2013). "Treatment of mice with a TLR2/6 agonist (Pam2CSK4, “Pam2”) alone or a TLR9 agonist (ODN2395, “ODN”) alone resulted in no protection against lethal influenza pneumonia." (PMID 22299046, 2012).
glioma (58 papers, 2012 to 2026). A benign or malignant brain and spinal cord tumor that arises from glial cells (astrocytes, oligodendrocytes, ependymal cells). "These factors (GDF) can induce one of the receptor, toll-like receptor 2 (TLR2) expression in microglia associated with gliomas, supporting tumor progression and invasion." (PMID 41268299, 2025). "MMP14 works through a specific crosstalk mechanism in which glioma-associated microglia upregulate TLR2, and glioma cells increase the expression of TLR2 ligand versican." (PMID 38473812, 2024). "Versican, released from gliomas, promotes tumor expansion through glioma-associated microglial/macrophage TLR2 signaling and subsequent expression of MT1-MMP." (PMID 36980765, 2023). "GL261 glioma-derived soluble factors can activate Toll-like receptor 2 (TLR2), which is highly expressed in tumor-associated microglia." (PMID 35920986, 2022). "Considering the heterogeneous nature of gliomas, ranging from low to high grade with different therapeutic responses, investigating the differences in the levels of TLR2 and TLR4 and associated inflammatory markers in these distinct groups is of great clinical significance." (PMID 40809181, 2025). "Additionally, TLR2 expression is induced in glioma-associated macrophages (GAM) by glioma cells provoking the transcription of MMP-9 and MMP-14, and cancer growth and spread." (PMID 38069210, 2023). "The overexpression of TLR2 and TLR4 has been previously documented in glioma cell lines and tissue samples, with both receptors implicated in promoting glioma tumorigenesis." (PMID 40809181, 2025). "TLR2 expression was significantly higher in the high-grade glioma group compared to the low-grade group." (PMID 40809181, 2025). "Pam3CSK4 and MALP2, two TLR2 antagonists, cause an increase in MT1-MMP expression, which aids in the growth and progression of gliomas." (PMID 40727443, 2025). "More specifically, TLR2 contributes to glioma progression by fostering an immunosuppressive tumor microenvironment (TME)." (PMID 41157253, 2025). "For example, TLR2 is upregulated by glioma cells to promote the degradation of the extracellular matrix, which promotes further tumor growth." (PMID 38893093, 2024). "TLR2 also plays pathological roles in glioma, including immune evasion and the development and progression of glioma cells." (PMID 37723542, 2023). "The upregulation of toll-like receptor 2 (TLR-2) on testosterone-treated glioma cell lines increases their recognition by innate immune cells as normal cells." (PMID 37833789, 2023). "Triller and coworkers have investigated the impact of vanillin, as a TLR-2 inhibitor, to block the TLR2-mediated microglia pro-tumorigenic phenotype using in vitro and in situ microglia–glioma interaction experimental models." (PMID 36768141, 2023). "For instance, glioma cells can secrete versican, which promotes the activation of microglia through the Toll-like receptor 2 (TLR2) signaling pathway." (PMID 36969167, 2023). "In this context, glioma-derived versican was identified as tumor-derived DAMP activating TLR2 on macrophages/microglia." (PMID 36224342, 2022). "The differential gene analysis in the current study showed that CASP4 expression is associated with several other important molecules of pyroptosis, including GSDMD, CASP1, IL-18, and TLR2, in gliomas." (PMID 36713560, 2022). "The study has shown that glioma induces chronic inflammation in microglia and activates Toll-like receptor 2 (TLR2), triggering downstream MAPK/ERK signaling, and responses associated to loss of histone H3 acetylation at CIITA promoters." (PMID 35711434, 2022). "In a screen for endogenous ligands secreted from glioma cells, versican was identified as a candidate molecule for triggering TLR2 signaling cascade." (PMID 35600367, 2022). "TLRs signaling pathways play an important role in the interaction between microglia and glioma, among which TLR2 is considered to be the main TLR that triggers MT1-MMP upregulation in microglia." (PMID 35600367, 2022).
glioma (continued). "An antibiotic, minocycline, significantly reduced MMP-9 production and TLR-2 expression in microglial cells treated with glioma conditioned medium." (PMID 34439380, 2021). "On the other hand, in pathological conditions such as glioma genesis, the tumor cells express TLR-2, -4, and -9." (PMID 34439380, 2021). "The finding that the mouse GL261 glioma cells inoculated in Tlr2 knockout mice grow a smaller tumor leading to longer survival of the host compared to the control indicates that the TAMs promote glioma progression via TLR2 signaling." (PMID 34671362, 2021). "TLR2 was found substantially elevated in glioma cell lines and tissues and inversely correlated with GBM patient survival." (PMID 34715891, 2021). "Another study has demonstrated that the decreased levels of MTI-MMP in TLR-2 knock out (KO) mice were correlated with a decrease in glioma size and better survival rate." (PMID 34439380, 2021). "TLR2 has also been found to regulate MMP9 production by microglia to promote glioma growth and invasion." (PMID 33766119, 2021). "Toll-like receptor 2 regulates glioma invasion by promoting the expression of matrix metalloproteinases." (PMID 33750478, 2021). "TLR2 knockout in glioma mouse model significantly reduced GAM accumulation and led to tumor regression and survival benefit." (PMID 34715891, 2021). "Pam3CSK4 increased the migratory and invasive capability of GSCs by enhancing MMP-2 and MMP-9 expression, while TLR2 knockout attenuated the effects and prolonged survival in glioma mouse model." (PMID 34715891, 2021). "We have shown that the endogenous ligand versican activates TLR2 in GAMs and is an important pathway for glioma-GAM communication." (PMID 32331440, 2020). "Microglial upregulation can be abolished by targeting TLR2, with potential therapeutic benefits in glioma progression." (PMID 33155039, 2020). "The expression of TLR2 in glioma samples, which consists of up to 30% of microglia/macrophages, is inversely correlated with patients’ overall survival." (PMID 32331440, 2020). "The expression of TLR2 and MMPs in glioma tissue was found to be inversely correlated with patients’ median survival according to TCGA analysis." (PMID 32331440, 2020). "TLRs play an important role for the interaction of microglia with glioma cells promoting a pro-tumorigenic phenotype including TLR2, TLR4, and TLR7 signaling." (PMID 32912327, 2020). "This upregulation is induced by versican released from glioma cells which signals via toll like receptor 2 (TLR2)." (PMID 32331440, 2020). "The TLR2 pathway has been established as a tumor promoting component in different malignancies like ovarian carcinomas, melanomas, or gliomas." (PMID 32331440, 2020). "In microglia sorted from rat C6 gliomas, genes characteristic for M1 activation: Tlr2, Tlr4 and Il18, Cd80, Il12a, Il15 were significantly downregulated." (PMID 29242629, 2017). "Analogously, cannabinoids suppress peptidoglycan-stimulated cell growth of a glioma cell line via TLR2 with concomitant decreased NF-κB activation." (PMID 27597805, 2016). "The expression levels of TLR2 are substantially elevated in patient glioma biopsies and inversely correlate with patient survival." (PMID 25411122, 2014). "Under this treatment strategy, nearly half of the mice bearing intracranial GL261 gliomas achieved long-term survival and anti-glioma immunological memory in a TLR2 dependent manner." (PMID 25411122, 2014). "In contrast to its role in glioma-derived microglia, TLR2 expression on DCs is of potential benefit to immunogenic glioma cell lysis." (PMID 25411122, 2014). "Based on these results and the fact that the molecule is highly expressed in human gliomas, TLR2 was examined as a potential biomarker, and its expression was found to be inversely correlated to patient survival." (PMID 25411122, 2014). "Weighing the balance in the dual character of TLR2 therefore appears to be an important consideration in the development of anti-glioma immunotherapies." (PMID 25411122, 2014).